Y_RNA (Y RNA )
Gene: Miscellaneous RNA gene on chromosome 15 (90,977,208 to 90,977,305, reverse strand). Ensembl gene ENSG00000200142.
Homologues: Orthologues: chimpanzee Y_RNA (100% identical), macaque Y_RNA (88% identical), dog Y_RNA (83% identical), pig Y_RNA (76% identical), guinea pig Y_RNA (74% identical). Paralogues in human: Y_RNA (84% identical), Y_RNA (83% identical), Y_RNA (82% identical), RNY3 (81% identical), Y_RNA (81% identical), Y_RNA (80% identical), RNY3P1 (79% identical), RNY3P14 (79% identical), Y_RNA (79% identical), RNY3P16 (78% identical), Y_RNA (78% identical), RNY3P4 (77% identical), and 89 more.